FOXM1 (forkhead box M1)
Diseases named in the same sentence as FOXM1 in open-access papers (continued):
Sharing a sentence is not in itself a finding about the gene and the disease.
tumor (continued). "In summary, deletion of Foxm1 in respiratory epithelial cells prior to or even after tumor initiation caused a striking decrease in the number and size of lung tumors." (PMID 19672312, 2009). "Immunohistochemistry demonstrated that decreased numbers and size of lung tumors in epFoxm1−/− lungs were associated with reduced Foxm1 expression and decreased proliferation in tumor regions." (PMID 19672312, 2009). "In another series of experiments, Dox was given one week after BHT treatment, causing Foxm1 deletion after tumor initiation." (PMID 19672312, 2009). "Furthermore, RA therapy targeted genes implicated in tumour progression and aberrant cell proliferation and downregulated the oncogenic transcription factor forkhead box M1 (FOXM1)." (PMID 40427522, 2025). "We discuss how PD-L1 and FOXM1, a tumor-promoting transcription factor, are functionally linked and may be key mediators of resistance to CDK4/6-MEK targeted therapies." (PMID 39347707, 2024). "Thus, defects in FOXM1 regulation confer proliferative advantages to cells but render them more susceptible to tumor-assisted transformation by oncogenes." (PMID 39594778, 2024). "The upregulation and activation of FOXM1 can lead to a variety of tumor-associated phenotypes such as cell proliferation, tumor stem cells, drug resistance, invasion, metastasis, and angiogenesis, which have been reported as top-level gene expression biomarkers with poor prognosis." (PMID 37667311, 2023). "Notably, FOXM1 expression exhibited significant associations with age (P = 0.016), tumor stage (P = 0.009), grade (P = 0.008), vascular invasion (P = 0.012), and hepatic inflammation (P = 0.001)." (PMID 37817774, 2023). "FOXM1, as an oncogenic transcription factor, plays vital functions in regulating various biological processes, the dysregulation and activation of FOXM1 cause tumor progression; it is also involved in epithelial–mesenchymal transition (EMT), metastasis, invasion, as well as carcinogenesis." (PMID 37159818, 2023). "As FGFR3 expression (activating mutations and/or copy number amplifications) is associated with low-grade tumours, FOXM1 regulon activity could be driving the transition from low- to high-grade NMIBC." (PMID 35655252, 2022). "In addition, FOXM1 is linked to the enhanced expression of stem cell markers in tumor samples, thereby promoting stem cell properties." (PMID 36428807, 2022). "The promoting role of FOXM1 in the invasion phenotype of GC cells, which was demonstrated in our previously study, also reflect by the positive association between the average fluorescence intensity of FOXM1 and tumor invasion depth." (PMID 36401232, 2022). "Furthermore, the association of FOXM1 expression with prognosis, clinical features, tumor-infiltrating immune cells, TMB, MSI, and immune checkpoint was investigated." (PMID 36435510, 2022). "Further, in vivo assays supported that loss of circ-FOXM1 restrained OS tumor growth." (PMID 35799265, 2022). "In addition, overexpression of FOXM1 is associated with an aggressive tumor feature and poor prognosis of HCC." (PMID 34539442, 2021). "Thus, identifying the regulatory mechanism that underlies FOXM1 upregulation is important for further understanding the tumorigenic process and enabling the development of new strategies for tumor prevention and therapy." (PMID 34740322, 2021). "Furthermore, the high-expressed FoxM1 is associated with poor prognosis, so this molecule is a biomarker of malignancy of tumor." (PMID 33526768, 2021). "FoxM1 is highly expressed in embryonic mouse tissues with a high proliferation index, such as thymus, small intestine and testicles, and it is also elevated in a variety of tumour tissues and is associated with tumour malignancy and patient prognosis." (PMID 32667745, 2020). "High levels of FOXM1 were found in tumor cells and tumor-associated macrophages." (PMID 32271749, 2020).
tumor (continued). "Moreover, OPN expression in stromal cells and FOXM1 expression in tumor cells were associated with poor clinical outcome." (PMID 30367545, 2019). "Moreover, FOXM1 expression in tumor cells was found to be obviously associated with pT status (P = 0.014) and marginally significant with pM status (P = 0.095)." (PMID 30367545, 2019). "Here, we show the ability of this miRNA to downregulate the aberrantly expressed transcription factor FOXM1, leading to a reduced proliferation rate, loss of colony formation, tumor invasion and induced programmed cell death through activation of the caspase 3/7 pathway in MB cells." (PMID 31541075, 2019). "Taken together, overexpressed FOXM1 induces VEGF secretion in TME and thus triggering nutrients supply to the tumour cells; on the other hand, increased levels of FOXM1 are closely associated with the development of chemotherapeutic resistance, which further promotes tumour growth and survival." (PMID 29180117, 2018). "During EMT, cells gain a migratory and invasive phenotype that is characteristic for mesenchymal cells; this phenotype has been recently linked to the resistance of the tumor to radiotherapy, particularly through FOXM1 a well-known actor of this mesenchymal transition." (PMID 30167084, 2018). "Survival analysis, with respect to gene expression, after age and tumor stage adjustments, revealed that high FOXM1 expression was associated with a poor ESCC patients prognosis, presenting a 2.73-fold increase of the risk of death (p = 0.03; 95% CI 1.11-5.93)." (PMID 29682174, 2018). "For example, miRNA-214 acts as a tumor repressor during the process of migration, and invasion, and is associated with sensitivity to cisplatin in cervical cancer via directly binding to the 3’UTRs of FOXM1 mRNA." (PMID 30208972, 2018). "Thus, we propose that FoxM1 is a candidate tumor promotor for the risk stratification and treatment of ICC." (PMID 30580327, 2018). "In 113 cases, FoxM1 expression was positively associated with tumor infiltration." (PMID 30416986, 2018). "High expression level of FOXM1 was also associated with advanced tumor stage." (PMID 28427178, 2017). "Notably, our study shows a significant association between the nuclear localization of FOXM1 in the tumor and the response to cetuximab therapy." (PMID 28423516, 2017). "Therefore, there is a significant association between the presence in the nucleus of tumor cells of FOXM1 transcription factor and patient response to anti-EGFR treatment with cetuximab." (PMID 28423516, 2017). "Notably, FOXM1 overexpression at diagnosis was significantly associated with tumor progression (P = 0.025)." (PMID 25537512, 2015). "FOXM1 is a key regulator of periodic gene transcription at the G2-M phase of the cell cycle and therefore thought to be linked to the increased proliferative nature of tumours." (PMID 25889361, 2015). "In addition, FOXM1 overexpression has been linked with tumor aggressiveness and with the accumulation of genomic alterations." (PMID 26008846, 2015). "FOXM1 is a member of a family of transcription factors that regulate the expression of genes essential for cell proliferation and transformation and are implicated in tumorigenesis and tumor progression." (PMID 26640950, 2015). "The C1 signature very effectively stratified the patients based on clinical outcome, indicating that FOXM1 regulatory sites and associated target genes may play a pivotal role in tumor progression and TAM resistance." (PMID 25213081, 2014). "Interestingly, re-expression of Foxm1 in SPDEF-deficient tumor cells restored cell migration, coinciding with elevated levels of MMP2, MMP9 and MMP13." (PMID 25254494, 2014).
tumor (continued). "Alternatively, it is also possible that the formation of lung tumors in epFoxm1−/− mice may result from secondary mutations that allowed tumor formation, bypassing proliferation defects in Foxm1-deficient lung tumor cells." (PMID 19672312, 2009). "Both types of experiments demonstrated that epFoxm1−/− mice were resistant to lung tumorigenesis as demonstarated by comparison of tumor numbers in Foxm1-deficient mice to either control Foxm1fl/fl mice, or triple transgenic epFoxm1fl/fl mice without Dox treatment." (PMID 19672312, 2009). "Using transgenic mice, we demonstrated that conditional deletion of Foxm1 from lung epithelial cells (epFoxm1−/− mice) prior to tumor initiation caused a striking reduction in the number and size of lung tumors, induced by either urethane or 3-methylcholanthrene (MCA)/butylated hydroxytoluene (BHT)." (PMID 19672312, 2009). "Notably, FOX family members exhibit diverse and sometimes opposing functions: while the FOXO subfamily is generally associated with tumor suppression and regulation of apoptosis, FOXM1 has been implicated in promoting cell cycle progression and oncogenic transformation." (PMID 40746724, 2025). "Additionally, FOXM1 is crucial in tumor development and is associated with poor prognosis." (PMID 37234166, 2023). "Since our previous study revealed that a positive correlation exists between FOXM1 and Wnt signaling, we decided to focus efforts on FOXM1 since it is a critical transcriptional coactivator of Wnt signaling, which is tightly linked to tumor growth and metastasis." (PMID 36072787, 2022). "In addition, the three-gene risk-score model (involving MFI2, FOXM1, and GPC3) for LUAD and the two-gene risk-score model (involving SERPINA1 and FOXM1) for LUSC might be useful in predicting the prognosis of tumour patients." (PMID 34112123, 2021). "As a classic proliferation-associated transcription factor, FOXM1 directly or indirectly activates the expression of target genes at the transcriptional level and exhibits a spatiotemporal pattern whose dysregulation is involved in almost all hallmarks of tumor cells." (PMID 30208972, 2018). "Moreover, the expression of FoxM1 was associated with tumor pathological grade." (PMID 29416660, 2018). "We speculate that the mechanism by which SP mediates DOX-induced chemoresistance in TNBC may be via activation of Forkhead box protein M1 (FOXM1, a transcription factor that is linked to increased survival of tumor cells) and programmed cell death 1 (PD-1, an immune surveillance escape factor)." (PMID 26981525, 2016). "The Cancer Genome Atlas (TCGA) gene expression data indicate that FOXM1 is markedly overexpressed in GBM clinical samples relative to non-tumor tissues." (PMID 41141395, 2026). "Because the FOXM1–VEGF/VEGFR2–Snail axis coordinates tumor growth, angiogenesis, and metastasis, targeting this pathway is a promising anticancer strategy." (PMID 41226369, 2025). "As a key transcription factor, FoxM1 plays a vital role in processes such as the proliferation, invasion, and metastasis of tumor cells." (PMID 41036313, 2025). "Expression of the differentiation marker IVL was increased after FOXM1 knockdown, while expression of basal marker tumor protein p63 (TP63) was decreased after knockdown even in the setting of IL-13 stimulation." (PMID 40501685, 2025). "Because FoxM1 has also been demonstrated to play essential roles in tumor angiogenesis, invasion, and metastasis, we evaluated changes in the antiangiogenic capacity by HO-1197 treatment using HUVECs." (PMID 41226369, 2025). "In this study, we find that the overexpression of the FOXM1 gene by a 3.5 log2FC in the HS tumor samples occurs in parallel with an increase in the expression of numerous cell-cycle- and mitosis-associated transcription targets of FOXM1." (PMID 40149290, 2025).
tumor (continued). "Reduced phosphorylation stabilizes FOXM1 condensates, leading to persistent hyperactivation of proto-oncogene transcription programs that fuel tumor progression and metastatic dissemination." (PMID 40723369, 2025). "Each of the four genes (HJURP, CDK1, FOXM1, and CHEK1) identified in the model has been implicated in cell cycle regulation and tumor development." (PMID 40299539, 2025). "Further analysis of the MMH cohort revealed that a high or low expression (transcript levels lower or higher than the cohort median) of KPNA2/FOXM1/CCNB1/CCNB2 is associated with ER, PR, HER2, and Ki67 status, molecular subtype, tumor grade, and AJCC stage." (PMID 40002266, 2025). "Our analysis revealed strikingly higher percentages of FOXM1-positive cells in the tumor groups compared to their normal counterparts." (PMID 39858603, 2025). "Another study demonstrated that FOXM1 promotes tumor progression and glycolysis in TNBC by regulating CENPA gene expression." (PMID 40092695, 2025). "Overexpression of CKS1B reversed the suppressed tumor growth, migration and CSCs self-renewal observed in FOXM1-knockdown cells compared to their control counterparts." (PMID 39897042, 2025). "Silencing FOXM1 significantly impairs tumor formation and metastasis and downregulates FOXM1 target genes involved in proliferation, migration, and invasion, suggesting FOXM1 is a key effector in LPA-induced tumorigenicity and ascites formation." (PMID 40746724, 2025). "Knockdown of FOXM1 inhibits the expression of cell cycle genes and suppresses cell proliferation, colony formation, and tumor growth." (PMID 40612352, 2025). "Because target genes of FoxM1 collectively promote tumor growth, metastasis, therapy resistance, and immune suppression, we analyzed FoxM1 expression in various cell types comprising the HCC microenvironment." (PMID 41226369, 2025). "FOXM1 has been identified as a direct target of miR-877, and miR-877 exerts its tumor-suppressive function by downregulating FOXM1 expression in OC cells." (PMID 40746724, 2025). "The positive feedback loop between lncRNA-PVT1 and FoxM1 plays a crucial role in promoting tumor growth and invasion." (PMID 40486884, 2025). "In NSCLC, these compounds also regulate non-coding RNAs such as the circ 0031250/miR-873-5p/FOXM1 axis, thereby suppressing tumor cell migration and invasion." (PMID 41480385, 2025). "For example, FOXOs, FOXCs, and FOXAs, as well as the prominent oncogene FOXM1, have been identified as regulators of tumour cell EMT." (PMID 39777582, 2025). "Studies have demonstrated that the FOXO3A/FOXM1 axis plays a critical role in tumor progression and chemoresistance." (PMID 40699718, 2025). "We found that FOXM1, AXL, and eEF2K are significantly overexpressed in GBM patient tumor samples and FOXM1 regulates the expression of AXL and eEF2K by physically interacting with these proteins." (PMID 40725039, 2025). "The LC1 subgroup was characterized by downregulation of genes associated with proliferation (i.e., FOXM1, MKI67) and lower G2M and E2F gene signatures, suggesting reduced rates of tumour growth." (PMID 41425537, 2025). "Multiple studies have revealed FOXM1’s significant role in regulating oxidative stress, contributing to malignant transformation and tumor cell survival, considering its overexpression in various human malignancies." (PMID 40561071, 2025). "These outcomes are partly consistent with one recent study in SCLC, where they have shown that FOXM1 plays an important role in SCLC tumorigenesis; however, they didn’t study the role of FOXM1 in metastasis, CR, and modulation of tumor immune cells." (PMID 40630538, 2025). "Various studies have aligned FOXM1 overexpression with heightened tumor grade, stage, and increased disease severity." (PMID 40612352, 2025). "It inhibits F‐box protein 31 (FBXO31), reducing ubiquitin‐mediated degradation of forkhead box M1 (FOXM1), ultimately leading to tumor progression and increased sorafenib resistance." (PMID 40060195, 2025).
tumor (continued). "Studies suggest FOXM1 overexpression confers malignant characteristics to tumor cells and thus plays a pivotal role in tumorigenesis, regulating tumor incidence, invasion and metastasis." (PMID 39762471, 2025). "FOXM1 upregulation impacts several fundamental tumor biological functions such as cell proliferation, apoptosis regulation, tissue invasion, metastasis, angiogenesis, stem cell properties of tumors, and alterations in metabolic processes." (PMID 40612352, 2025). "Inhibitors like thiostrepton, siomycin A, and the ARF26-44 peptide have demonstrated efficacy in suppressing FOXM1’s downstream gene targets and inhibiting tumor growth." (PMID 40002266, 2025). "FOXM1 consistently ranked among the topmost highly expressed genes in the tumor datasets, with highly significant adjusted p-values below threshold levels." (PMID 39858603, 2025). "FOXM1 is also upregulated in the tumor microenvironment, showing a marked upregulation in tumor cells compared to normal cells." (PMID 39858603, 2025). "As FOXM1 is a critical mediator of tumor cell survival, its suppression likely explains the observed reduction in colony-forming ability following chiglitazar treatment." (PMID 40959276, 2025). "Visualizing FOXM1 expression using UMAP plots further corroborated these observations: in the tumor datasets, we identified distinct clusters of cells exhibiting high FOXM1 expression levels." (PMID 39858603, 2025). "Differential motif analysis nominated AHR and FOXM1 as the most significant TF motif gained by the T>C change in the MECOM promoter, and RNA-seq data analysis confirmed the expression of AHR and FOXM1 in the tumor sample." (PMID 40355593, 2025). "Data from The Cancer Genome Atlas reveal that the FOXM1 gene locus is amplified in approximately 12% of high-grade serous ovarian carcinomas, a higher frequency than in any other tumor type." (PMID 40746724, 2025). "It has also been postulated to have tumoricidal activity, mostly related to its chemical inhibition of oncogenic transcription factor Forkhead box M1 (FOXM1) in tumor cells." (PMID 40820379, 2025). "Combining FOXM1 inhibitors, particularly with immune checkpoint inhibitors, is expected to open new tumor therapy avenues." (PMID 40612352, 2025). "The outcomes of recent studies have attracted the interest of the scientific community to evaluate the efficacy of FOXM1 inhibitors in different tumor types." (PMID 40630538, 2025). "In multiple experimental models, FOXM1 promotes tumor cell proliferation by sustaining proliferative signaling and evading growth-inhibitory factors, which enhances cell viability and expedites cell cycle progression." (PMID 40612352, 2025). "EPZ-6438 primarily inhibits cell cycle progression and proliferation in vitro in IOMM-Lee tumor cells, along with decreased FOXM1 and increased p21 expression." (PMID 40718644, 2025). "Collectively, our data strongly indicate that FOXM1 upregulates CKS1B expression transcriptionally in PDAC cells and CKS1B is instrumental in mediating FOXM1-driven tumor proliferation, migration, and stemness, thereby promoting tumor progression." (PMID 39897042, 2025). "In the FOXM1 paradigm where hypophosphorylated IDRs stabilize oncogenic condensates, the disruptive peptide FIP4 successfully inhibits tumor progression by dissolving phase-separated FOXM1 condensates." (PMID 40723369, 2025). "FOXM1 is a proliferative transcription factor that is widely expressed in actively dividing cells, including stem cells and tumor cells." (PMID 40092695, 2025). "On this basis, the development of anti-tumor drugs FOXM1 inhibitors will also bring hope for the diagnosis and treatment of CC." (PMID 40589640, 2025). "FOXM1 plays a critical role in regulating T-cell proliferation and survival, and it has potential regulatory functions in T-cell-mediated anti-tumor immune responses." (PMID 40282426, 2025).